VIP (vasoactive intestinal peptide)
Diseases named in the same sentence as VIP in open-access papers (continued):
Sharing a sentence is not in itself a finding about the gene and the disease.
colorectal cancer (5 papers, 2016 to 2023). A primary or metastatic malignant neoplasm that affects the colon or rectum. "Elevated VIP secretion is associated with advanced tumor stage in colorectal carcinoma." (PMID 29915691, 2018). "A study has shown an increase in the density of VIP-expressing myenteric fibers in experimental colorectal carcinoma, highlighting their cytotoxic effect against tumor cells, but with no accompanying changes in neuronal density." (PMID 27635657, 2016). "Thereby, the inhibition of VIP signaling may be a promising therapeutic target in colorectal cancer treatment." (PMID 36650220, 2023). "The VIP and SST genes reported in another study that applied network-based algorithms to find prognostic markers in colorectal cancer." (PMID 35486660, 2022). "Therefore, the inhibition of VIP effects, particularly via VPAC2 in macrophages, may be a promising therapeutic target to treat colorectal cancer." (PMID 36650220, 2023). "However, PACAP KO mice resulted in higher mortality rates and colorectal cancer development not seen in VIP KO mice." (PMID 31849864, 2019).
experimental autoimmune encephalomyelitis (5 papers, 2012 to 2022). An autoimmune demyelinating disease of the central nervous system that is produced experimentally in animals by the injection of homogenized brain or spinal cord in Freund's adjuvant. "VIP was reported to have protective effects on the focal ischemia of the brain and be a potential therapeutics for experimental autoimmune encephalomyelitis (EAE)." (PMID 31921708, 2019). "In addition, we have recently reported that despite the well-described anti-inflammatory actions of VIP, VIP KO female mice were unexpectedly resistant to experimental autoimmune encephalomyelitis (EAE) induction, with reduced immune cell infiltration of the spinal cord and brain parenchyma." (PMID 22615845, 2012).
heart attack (5 papers, 2009 to 2024). "In this study, the miR-662/CREB1/VIP regulatory pathway was successfully constructed by integrating AF and heart attack datasets." (PMID 34853624, 2021). "Therapeutic potential was evaluated in a rat model of myocardial infarction using nanofiber-expanded human cord blood derived hematopoietic stem cells (CD133+/CD34+) genetically modified with VEGF plus PDGF genes (VIP)." (PMID 19809493, 2009). "Additionally, we explore GA′s proficiency in eliciting an increase in the plasma levels of vasoactive intestinal peptide, which by dilating the blood vessel consequently, can be a crucial aid during the occurrence of a potential heart attack." (PMID 27689971, 2016). "Reports indicate an increase in VIP release during myocardial infarction, potentially acting as a protective mechanism, and it is released into the coronary circulation in both normal and diseased hearts, suggesting VIP may have a critical role in modulating cardiac function." (PMID 37029787, 2024).
injury (5 papers, 2018 to 2025). Damage inflicted on the body as the direct or indirect result of an external force, with or without disruption of structural continuity. "Experimental studies utilizing both dry eye guinea pig models and LPS-induced acute lung injury rat models have provided compelling evidence that VIP modulates AQP5 expression and macrophage M1/M2 polarization via the cAMP-PKA signaling axis." (PMID 41034926, 2025). "VIP is able to prevent activated microglia-induced neurodegeneration in models of brain trauma in mice, confirming its immune-modulatory role in vivo." (PMID 34681607, 2021). "In our study, both induced high levels of SP and VIP were observed in HEV inoculated animals, revealing the critical immunoregulatory function of SP and VIP in HEV induced brain injury." (PMID 31921708, 2019).
leukemia (5 papers, 2018 to 2025). A malignant (clonal) hematologic disorder, involving hematopoietic stem cells and characterized by the presence of primitive or atypical myeloid or lymphoid cells in the bone marrow and the blood. "Preclinical models of murine AML treated with a VIP receptor antagonist showed immune-cell-mediated leukemia eradication, with long-term survival rates of 40% in VIP-negative cases and 75% in VIP-positive models." (PMID 40909943, 2025). "The limited potency of the VIP antagonist peptide VIPhyb in T-cell activation and murine anti-leukemia models prompted the development of a more potent antagonist." (PMID 41478571, 2025). "Petersen, C T, Li, J M, & Waller, E K, Administration of a vasoactive intestinal peptide antagonist enhances the autologous anti-leukemia T cell response in murine models of acute leukemia." (PMID 30400835, 2018). "We have previously shown that daily administration of VIPhyb, a competitive peptide antagonist of VIP signaling, improves overall tumor free survival in mouse models of leukemia." (PMID 30400835, 2018). "This pathway could contribute to mitochondrial quality control in leukemia cells, offering a potential mechanistic link between VIP and mitophagy in AML." (PMID 40873580, 2025). "Additionally, in murine leukemia models, we have observed that inhibiting vasoactive intestinal peptide (VIP) signaling reduces tumor burden and increases survival." (PMID 30400835, 2018). "VIP and PACAP suppressed tumour cell proliferation of human leukaemia myeloid cells." (PMID 35011543, 2022). "Exposure of VIP and PACAP increased cAMP level in three out five tested human leukaemia cell lines." (PMID 35011543, 2022).
metabolic syndrome (5 papers, 2012 to 2023). A cluster of metabolic risk factors for CARDIOVASCULAR DISEASES and TYPE 2 DIABETES MELLITUS. "Additionally, the expression of EPGN, LGR5, NCK1, PGRMC2, and VIP were also comfired at transcriptional using qPCR, indicating that those genes are closely linked to dyslipidemia in OSA." (PMID 34880901, 2021). "Currently, there is a relative paucity of studies that investigate the role of PACAP and VIP in the treatment of metabolic syndrome." (PMID 37508442, 2023).
mood disorder (5 papers, 2021 to 2024). A cognitive disorder a disturbance in which the person's mood is hypothesized to be the main underlying feature. "Therefore, we infer that VIP may have a potential therapeutic effect on patients with PD associated with mood disorders, which also provides a new research direction for the treatment of neurodegenerative diseases with mood disorders." (PMID 34566619, 2021). "Enrichment for brain-related disorders within the upregulated DE genes included demyelinating disease (in microglia), mood disorders (in VIP inhibitory neurons) and substance abuse (in oligodendrocytes)." (PMID 39227716, 2024). "The non-motor symptoms significantly negatively correlated with serum PACAP level was cognitive dysfunction, while mood disorder was significantly correlated with serum VIP level." (PMID 34566619, 2021). "At the same time, PACAP levels in relation to cognitive function and VIP levels in relation to mood disorders were proven." (PMID 34566619, 2021). "Excitingly, this novel mouse model suggests that VIP neurons might provide a shared neurological underpinning between reproductive and mood disorders." (PMID 38205198, 2023). "Taken together, these data point to a novel role of VAX1 in regulating VIP neuron modulation of mood and the reproductive axis and raise the potential of Vax1Vip females to serve as a new model for mood disorders that are tied to reproductive cycles, such as PMDD." (PMID 38205198, 2023). "Lower PACAP levels could be measured in the cognitive dysfunction subgroup compared to the cognitive intact subgroup, while mood disorder significantly correlated with serum VIP level." (PMID 35220508, 2022). "Therefore, it is speculated that the occurrence of mood disorders in PD patients has a certain relationship with internal VIP levels." (PMID 34566619, 2021). "Therefore, PACAP and VIP levels can be used to evaluate PD-related non-motor symptom–cognitive function and mood disorders, respectively." (PMID 34566619, 2021).
type 2 diabetes (5 papers, 2012 to 2022). "The loss of AVP-ir and VIP-ir SCN neurons, therefore, could result in a disbalanced autonomic hypothalamic output, as often observed in type 2 diabetes." (PMID 31327049, 2019). "This review summarizes the physiological significance of VIP in glucose homeostasis and the potential therapeutic value of VPAC2-selective agonists in type 2 diabetes." (PMID 36204104, 2022). "This review summarizes the physiological significance of VIP in glucose homeostasis and the therapeutic potential of VPAC2-selective agonists in the treatment of type 2 diabetes." (PMID 36204104, 2022). "Our data show that type 2 diabetes differentially affects the numbers of AVP- and VIP-expressing neurons and GFAP-ir astroglial cells in the SCN, each of which could affect the daily rhythmicity of the SCN biological clock machinery." (PMID 31327049, 2019). "The finding that GLP1, by way of VIP release, executes neuroprotection on myenteric neurons highlights the possibility of additional beneficial effects activated by the use of GLP1 receptor stimulation to achieve better metabolic control in type 2 diabetes clinically." (PMID 22463807, 2012).
Achalasia (4 papers, 2018 to 2024). A disorder of esophageal motility characterized by the inability of the lower esophageal sphincter to relax during swallowing and by inadequate or lacking peristalsis in the lower half of the body of the esophagus. "Deranged esophageal peristalsis and loss of LES function, due to imbalance between excitatory neurons releasing acetylcholine and inhibitory neurons that release NO and VIP, are the abnormalities and diagnostic characteristics of achalasia." (PMID 39337632, 2024). "Thus, polymorphisms in NOS, VIP and c-kit genes represented ideal candidates to explain the inflammation and the inhibitory neurotransmission observed in achalasia." (PMID 39337632, 2024). "Decreased levels of the nitric oxide synthase (NOS) and vasoactive intestinal polypeptide (VIP) as inhibitory neurotransmitters in the myenteric plexus disrupt esophageal neuromuscular function in the patients with achalasia." (PMID 34377051, 2021). "Additionally, we documented achalasia-associated autoantigens PNMA2, Ri, GAD65, and VIP as novel MMP-9 substrates." (PMID 30449890, 2018).
allergic asthma (4 papers, 2011 to 2022). A asthma with a basis in a pathological type I hypersensitivity reaction. "Exogenous VIP administered, decreases airway inflammation in an allergic asthma murine model, effect comparable ICS." (PMID 34055794, 2021). "Several animal and clinical trials suggest that VIP or VIP agonist treatment could be used for respiratory diseases, including acute lung injury, allergic asthma, and COPD (46, –, 48)." (PMID 36350149, 2022).
allergic rhinitis (4 papers, 2013 to 2024). Inflammation of the nasal mucous membranes caused by an IgE-mediated response to external allergens. "In patients with allergic rhinitis (AR), nasal cavity stimulation leads to a significant increase in neurocrine VIP content, and the secreted VIP recruits eosinophils through the CRTH2 receptor." (PMID 38331782, 2024). "Only one study has examined the effects of acupuncture on the proinflammatory neuropeptides SP and VIP in humans with allergic rhinitis." (PMID 23476696, 2013). "This emphasizes the significance of VIP innervation in allergic rhinitis." (PMID 38331782, 2024). "Acupuncture has already been shown to downregulate SP and VIP in allergic rhinitis and may also downregulate CGRP." (PMID 26339274, 2015). "Further studies are needed to elucidate some of the interactions between the neuropeptides: SP, CGRP, and VIP and the neurotrophins NGF and BDNF and some Th1, Th2, and proinflammatory cytokines in allergic rhinitis." (PMID 23476696, 2013). "The effect of BDNF on nerve fibers in AR has not been described; however, patients with allergic rhinitis have a greater number of vasoactive intestinal polypeptide (VIP)-positive nerve fibers in the mucosal tissue of the nasal conchae than control subjects." (PMID 37047077, 2023).
cholera (4 papers, 2018 to 2024). "Cyclic nucleotide–mediated (cAMP- or cGMP-mediated) CFTR activation and consequent Cl– secretion represent the key pathology in certain secretory diarrheas including cholera, and traveler’s diarrhea and diarrhea caused by vasoactive intestinal peptide–secreting (VIP-secreting) tumors (VIPomas)." (PMID 37962961, 2024). "Since diarrhea can be caused by raising VIP levels in either plasma, as in pancreatic cholera syndrome, or by release from nerve endings in the intestinal mucosa, we measured VIP levels in both plasma and cholera rice-water stool water." (PMID 32630790, 2020). "The growing body of evidence relating CT to VIP and gut fluid accumulation leading to diarrhea led us to repeat the earlier unpublished study to confirm a possible VIP role in human cholera pathogenesis." (PMID 32630790, 2020). "Cholera patients during profuse watery diarrhea had very high levels of VIP in their stool water, while plasma VIP levels remained normal." (PMID 32630790, 2020). "Studies performed on human tissues in vitro and on rats in vivo indicate that CT-induced secretion is predominantly mediated by VIP released by secretomotor neurons, as various VIP antagonists attenuate cholera hypersecretion." (PMID 29618987, 2018). "We aimed to determine whether vasoactive intestinal polypeptide (VIP), the mediator of pancreatic cholera syndrome, has a role in the pathophysiology of human cholera." (PMID 32630790, 2020). "High VIP levels in cholera patients’ stool water may reflect an important role of VIP in the pathophysiology of cholera diarrhea." (PMID 32630790, 2020). "At admission, cholera patients in shock had elevated plasma VIP (pVIP) levels." (PMID 32630790, 2020). "This is the first full prospective report of plasma and stool VIP levels in cholera patients." (PMID 32630790, 2020). "The current study shows a clear link bridging prior work to stool VIP in cholera patients." (PMID 32630790, 2020). "The findings suggest that human cholera diarrhea may be mediated by heightened intestinal neural production of VIP and luminal release of VIP, consistent with earlier in vitro and in vivo animal model studies suggesting participation of a neural/hormonal mechanism in pathogenesis." (PMID 32630790, 2020). "In addition to cholera or traveler’s diarrhea, cinacalcet may be effective in other forms of secretory diarrheas, such as VIPoma, as suggested by its efficacy in reducing VIP-induced secretory response in T84 cells and by its mechanism involving reducing cAMP levels in enterocytes." (PMID 33400691, 2021). "In patients with cholera and VIP-induced diarrhea, there is a lack of a stool osmotic gap, which indirectly suggests the possibility that stool Mg2+ concentrations might be low in these conditions." (PMID 37962961, 2024).
Chronic constipation (4 papers, 2017 to 2026). Constipation for longer than three months with fewer than 3 bowel movements per week, straining, lumpy or hard stools, and a sensation of anorectal obstruction or incomplete defecation. "Elevated levels of VIP can inhibit secretory activities and peristalsis, leading to chronic constipation." (PMID 39844840, 2024). "Elevated VIP levels can inhibit gastrointestinal smooth muscle contraction, reduce glandular secretion, and slow intestinal motility, leading to chronic constipation." (PMID 39844840, 2024). "Similarly, a decrease in the number of enteric neurons of submucosal plexuses containing VIP was detected by colonoscopy in parkinsonian patients with chronic constipation." (PMID 29255488, 2017). "However, chronic constipation could be attributed to abnormal peptidergic innervation of the colonic enteric nervous system, which may manifest as a reduction in VIP levels." (PMID 37296188, 2023). "In patients with PD and chronic constipation, submucosal colonic neurons downregulate vasoactive intestinal peptide (VIP) without neuronal loss, suggesting that constipation may arise from dysfunction rather than depletion of VIP‐ergic secretomotor neurons." (PMID 41486750, 2026).
cognitive decline (4 papers, 2020 to 2026). "In this review article, we first presented evidence showing the therapeutic potential of PACAP and VIP to fight the cognitive decline observed in models of AD, PD, and HD." (PMID 32765225, 2020). "Some data in animal models show that the lack of PACAP and VIP is associated with a cognitive decline." (PMID 32765225, 2020). "This suggests that inhibition of hippocampal LTP by VIP may be neuroprotective in conditions associated with aberrant synaptic plasticity, and that VPAC1 receptor ligands may constitute more efficient and safer drugs to treat cognitive decline in the aging or epileptic." (PMID 35625355, 2022). "Preclinical AD models show that neuroprotective neuropeptides, such as neuropeptide Y (NPY), vasoactive intestinal peptide (VIP), and pituitary adenylate cyclase-activating peptide (PACAP), exert neuroprotective effects, enhance memory, and attenuate cognitive decline." (PMID 41977389, 2026). "This brings into question the hypothesis that VIP VPAC1 receptor ligands, by fine-tuning disinhibition, may constitute more efficient and safer drugs to treat cognitive decline in the aging or epileptic." (PMID 35625355, 2022). "Unfortunately, no studies are exploring the capacity of PACAP and VIP to fight the cognitive decline in ALS and MS." (PMID 32765225, 2020).
Diarrhea (4 papers, 2016 to 2021). Abnormally increased frequency (usually defined as three or more) loose or watery bowel movements a day. "PYY inhibited Prostaglandin E2 (PGE2) and Vasoactive Intestinal Peptide that stimulated intestinal water secretion in the human small intestine being a defence against diarrhoea." (PMID 34148100, 2021). "That patient suffered from Verner-Morrison syndrome, i.e. watery diarrhea hypokalemia hypochlorhydria (WDHH) syndrome, also known as VIPoma (vasoactive intestinal peptide) or pancreatic cholera and experienced hypokalemic paralysis caused by massive gastrointestinal potassium loss." (PMID 27682153, 2016).
diverticular disease (4 papers, 2013 to 2015). A complex disorder characterised by mucosal outpouchings (diverticulae) of the colonic wall which can become infected and inflamed leading to diverticulitis, perforation and bleeding. "Disturbances in the normal neural content of VIP in the bowel wall in idiopathic constipation and diverticular disease may initiate or contribute to the functional changes observed in these disorders." (PMID 23935751, 2013).
dyspepsia (4 papers, 2020 to 2025). An uncomfortable, often painful feeling in the stomach, resulting from impaired digestion. "PWS had therapeutic effects in rats with functional dyspepsia by influencing both brain–gut substance P and vasoactive intestinal peptide levels." (PMID 33584294, 2020). "Other studies have found that rats with functional dyspepsia had lower levels of GAS and MTL in their serum, while VIP levels were significantly increased." (PMID 41394914, 2025).
Erythema (4 papers, 2012 to 2025). Redness of the skin, caused by hyperemia of the capillaries in the lower layers of the skin. "On stimulation, the nerves rapidly release active neuropeptides such as CGRP, tachykinins, and vasoactive intestinal peptide (VIP), then they act on target cells resulting in erythema, edema, hyperthermia, and pruritus associated with sensitive skin symptoms." (PMID 21912567, 2012).